CRP (C-reactive protein)
Diseases named in the same sentence as CRP in open-access papers (continued):
Sharing a sentence is not in itself a finding about the gene and the disease.
Hypertension (continued). "The present study showed that levels of circulating biomarkers of inflammation, CRP, and oxidative stress, oxLDL, are higher in lone AF patients compared to healthy individuals and that both biomarkers were associated with increased risk for incident hypertension in lone AF." (PMID 26229238, 2015). "Moreover the CRP elevation in farmers may contribute to an increased risk of hypertension, myocardial infarction and stroke as well." (PMID 23442558, 2013). "In addition, maternal CRP levels were positively associated with diastolic blood pressure, and elevated CRP levels were associated with pregnancy-induced hypertension and preeclampsia, but these associations attenuated toward the null after adjustment for maternal body mass index." (PMID 22306530, 2012). "A growing amount of evidences suggest that inflammation participates in the pathogenesis of hypertension, and hypertension may be in part an inflammatory disease because C-reactive protein level, a marker of systemic inflammation, is associated with future development of hypertension." (PMID 22682236, 2012). "Therefore the increased CRP in Caucasian women could feasibly cause endothelial dysfunction, which in turn could lead to hypertension and subsequent cardiovascular dysfunction." (PMID 22447476, 2012). "Since rs1061170 (Y402H) and rs2274700 (A473A) are both located at the CRP-binding site in CFH, we therefore tested whether there was an interaction between plasma CRP levels and genotypes of these two SNPs for association with blood pressure or hypertension risk." (PMID 22848687, 2012). "Additionally, it has been demonstrated both in vitro and in vivo that CRP impairs endothelial vasoreactivity, and hence could increase the risk for hypertension." (PMID 21296145, 2011). "The ISR (+) group showed a higher prevalence of hypertension and active smoking, as well as higher CRP, glucose, and neutrophil levels, but lower albumin and lymphocytes (all p < 0.05)." (PMID 41827923, 2026). "Significant differences between severity groups were also observed for age, hypertension, creatinine, hemoglobin, platelet count, D-dimer/CRP ratio, and PA diameter (all p < 0.05)." (PMID 42200059, 2026). "CRP and depression (RDS-4 score) together explained 11.7% (7.65, 17.4) of the association between chronic pain and risk of hypertension." (PMID 41243808, 2026). "Based on clinical assessments, body mass index, LDL cholesterol, C-reactive protein, systolic blood pressure, diastolic blood pressure, hypertension, and smoking status were measured." (PMID 41657545, 2026). "High IL-6 correlated with Black race, higher BMI, hypertension, and markers of metabolic dysfunction, e.g., elevated HbA1c, C-reactive protein (CRP), and reduced lung function." (PMID 39714726, 2025). "High CRP levels indicate poor high-density lipoprotein cholesterol and hypertension, which are often identified in these patients." (PMID 40662069, 2025). "NHANES data highlighted body mass index (BMI), stroke, hypertension (HBP), and C-reactive protein (CRP) as key DR risk factors, confirmed by MR." (PMID 41340073, 2025). "Performing logistic regression analysis, by inserting all investigated variables as covariates, BMI, hypertension, FV Leiden mutation, FII 20210G>A mutation, CRP, and NPB-α2-PI antigen levels showed a significant association with the occurrence of VTE." (PMID 41303634, 2025). "Univariate analysis indicated that age, sex, WBC, RDW, BUN, LDL-C, FBG, hs-CRP, hypertension, DM, and AF were correlated with worse outcome (all p < 0.05)." (PMID 40177410, 2025). "Results such as higher DM prevalence and CRP levels in patients with hypertension with PAD, as well as the independent correlation of CRP levels with PAD, align well with current evidence." (PMID 40361914, 2025).
Hypertension (continued). "A study conducted among Ghanaian migrants and their homeland counterparts found that high levels of C-reactive protein (CRP), a marker of inflammation, were associated with hypertension in urban Ghanaian women and European–Ghanaian men and women." (PMID 40427895, 2025). "Independent risk factors included perioperative blood transfusion, elevated C-reactive protein, D-dimer >500 μg/L, hypertension, age ≥60 years, and prolonged bed rest." (PMID 41050348, 2025). "When the definitions of hypertension and hs-CRP were further modified, the highest HR values were virtually the same." (PMID 41235334, 2025). "The dietary approaches to stop hypertension score (DASH-S) demonstrated a significant positive association with adiponectin and an inverse association with CRP in early pregnancy and other proinflammatory biomarkers (TNF-α and IL-6)." (PMID 40043850, 2025). "After adjustment for baseline age, gender, BMI, smoking status, alcohol consumption, hypertension, FPG, CRP and TC, there was an increase in the risk of T2DM of 9 percent for each increment of 1 in BLR value (model 3)." (PMID 40491590, 2025). "Here, apparently healthy patients are referred to as those unaffected by significant vascular conditions and, if any, affected by hypertension, mild dyslipidemia, or CRP increases, as well as recent-onset diabetes." (PMID 40149635, 2025). "Studies have also shown that CRP levels are higher in individuals with specific components of metabolic syndrome, such as abdominal obesity, insulin resistance, and hypertension." (PMID 40093747, 2025). "The univariate logistic regression analysis showed that the POD incidence was positively correlated with being male, polypharmacy, hypertension, hemoglobin, albumin, and C-reactive protein (p-value < 0.1)." (PMID 40005452, 2025). "CRP can also promote the proliferation of vascular endothelial cells and increase arterial wall thickness, contributing to hypertension." (PMID 39484785, 2025). "Hype in CRP in these patients signifies not only an extent of airway inflammation but also evidence of co-morbid conditions such as hypertension, cardiovascular disease and obesity." (PMID 40662069, 2025). "After adjustment for baseline age, gender, BMI, smoking status, alcohol consumption, hypertension, FPG, CRP and TC, there was an increase in the risk of T2DM of 8 percent for each increment of 1 in BLR value (model 3)." (PMID 40491590, 2025). "In contrast, in the non-geriatric group, well-being was most strongly influenced by the presence of arterial hypertension, as well as levels of CRP, hemoglobin, and leptin." (PMID 40806940, 2025). "Consistent with reports in critically ill patients, we observed lymphopenia, neutrophilia, and elevated levels of CRP, D-dimer, and ferritin, along with a high prevalence of hypertension and cardiovascular comorbidities." (PMID 40087795, 2025). "In the non-geriatric group, the key determinants were the presence of hypertension, along with CRP, hemoglobin, hematocrit, and leptin levels." (PMID 40806940, 2025). "Based on the results of our meta-analysis and the results of studies in adults, we can conclude that hs-CRP concentration is an important, repeatable biomarker of hypertension and cardiovascular burden in children." (PMID 40217768, 2025). "The univariate and multivariate analyses revealed that hypertension, CHF, Cor pulmonale, low DBP, elevated WBC count, neutrophil ratio, serum creatinine, CRP, and PCT, decreased albumin and platelets were associated with adverse outcomes." (PMID 41179861, 2025). "Inflammation is now recognized as a significant pathophysiological factor in hypertension, with various inflammatory markers such as CRP, cytokines, and adhesion molecules found to be elevated in patients with this condition." (PMID 40026346, 2025).
Hypertension (continued). "High LDL-C high CRP patients had higher hypertension history (66.4% vs. 53.9%, p = 0.002), prior MI history (4.3% vs. 1.0%, p = 0.026) and prior heart failure history (2.6% vs. 0.0%, p = 0.044) compared with high LDL-C low CRP patients." (PMID 40722610, 2025). "In our case report, the recipient presented with hypertension, incomplete graft function recovery prior to infection, and a post-infection CRP level exceeding 60 mg/l, indicative of severe COVID-19 infection." (PMID 40182852, 2025). "Individuals with hypertension often have elevated levels of pro-inflammatory markers, such as C-reactive protein (CRP), interleukin-6 (IL-6), TNF-α, and reactive oxygen species (ROS)." (PMID 39940640, 2025). "An ANCOVA analysis of the covariates in the female group using CKD-Epi after 48 months as a dependent variable revealed that besides CKD-Epi at inclusion and active treatment, hypertension and CRP also influenced the dependent variable." (PMID 40563319, 2025). "The remaining RCTs (7 RCTs, 22.6%) encompassed single studies related to diverse conditions such as obstructive sleep apnea, rheumatoid arthritis, polycystic ovary syndrome, elevated CRP, hypertension, schizophrenia, and HIV." (PMID 40440323, 2025). "Patients suffered from MACCE were older and more likely to have hypertension, DM, hyperuricemia, elevated uric acid (UA), higher CRP levels, and lower FFR value." (PMID 40084257, 2025). "This score exhibited a strong independent association with all-cause mortality, even after adjusting for key clinical risk factors such as age, sex, disease duration, hypertension, smoking status, HbA1c, BMI, LDL-C, and hs-CRP." (PMID 40629349, 2025). "The Low CRP group (< 3 mg/L) and the High CRP group (> 3 mg/L) were significantly different in gender, poverty-to-income ratio, body mass index, hypertension, hemoglobin (Hb), hematocrit, and mean corpuscular hemoglobin." (PMID 40087374, 2025). "Recent studies have similarly reported significantly elevated levels of these blood markers (VLDL, triglycerides, CRP, and WBC) in hypertensive patients compared with normotensive individuals, with CRP levels correlating with the severity of hypertension." (PMID 40572711, 2025). "Inflammatory biomarkers, particularly CRP, were consistently elevated in Zn-overloaded states, aligning with epidemiological evidence that CRP predicts future coronary events and hypertension." (PMID 41459237, 2025). "These include hypertension, dyslipidaemia, hyper-homocysteinaemia and increased levels of C-reactive protein, oxidative stress and blood viscosity." (PMID 39797106, 2024). "These factors include age, hypertension, sepsis or septic shock, renal injury, white blood cell count, blood calcium levels, C-reactive protein (CRP), creatinine, albumin, and hemoglobin (p < 0.05)." (PMID 38903514, 2024). "Among the diabetic patients, the lowest level of HbA1c group (HbA1c < 6.0%) had the highest levels of Scr and C-reactive protein and the highest proportion of hypertension." (PMID 38433248, 2024). "Continuous training significantly reduced blood pressure and CRP levels and improved ED and aerobic capacity in men with ED with hypertension." (PMID 39246645, 2024). "Patients in the persistently high hs-CRP group (Group D) were more likely to have comorbidities, including hypertension, AF, CKD, and history of heart failure and stroke." (PMID 39130048, 2024). "The number of patients with hypertension, blood pressure, fasting blood glucose, total cholesterol and C-reactive protein in the observation group were significantly higher than those in the control group (P<0.05, Table-I)." (PMID 38544995, 2024). "Of note, CRP is related to hypertension, arterial stiffness, and end-organ injury markers in hypertensive patients." (PMID 38791032, 2024).
Hypertension (continued). "Fábio Vidal and colleagues found that periodontitis therapy reduces plasma levels of Interleukin-6, C-Reactive Protein, and fibrinogen in patients with severe periodontitis and refractory arterial hypertension." (PMID 39298393, 2024). "For ClinicalTrials.gov, ScienceDirect, and the Cochrane Library, we used the search terms ‘Exercise AND CRP AND Hypertension’." (PMID 39246645, 2024). "Several cohort studies of normotensive individuals have found that elevated C-reactive protein (CRP) predicts the development of hypertension." (PMID 39558500, 2024). "Hypertension, glucose, glycohemoglobin A1c, neutrophil-lymphocyte ratio and ultrasensitive C-reactive protein to albumin ratio levels were highly significant in evaluating the prognosis of patients." (PMID 38903919, 2024). "In the literature, there are many arguments in favour of a particular relationship between hypertension and some inflammatory markers such as C-reactive protein (CRP)." (PMID 38792613, 2024). "In clinical studies, middle-aged and elderly participants with hypertension who were administered a daily dose of 2 g EPA + DHA for 90 days exhibited reduced plasma levels of CRP and Tnfα, while Il6 levels remained unaffected." (PMID 39683572, 2024). "A nomogram based on the variables hypertension, bowel emptying, current smoker, CRP, and WBC was constructed to estimate the probability of arterial occlusive AMI." (PMID 39682613, 2024). "As detailed in the Results, some in the Healthy BMI cohort exhibit individual measures outside of normal ranges, including hypertension together with a handful of subjects with elevated CRP or LDL." (PMID 38886825, 2024). "Log-transformed IL-6 and CRP levels also remained significantly higher after correcting for renal function, smoking and hypertension." (PMID 39012360, 2024). "In the field of cardiovascular disease research, biomarkers such as C-reactive protein (CRP), interleukin (IL), and tumor necrosis factor-alpha (TNF-α) are considered to be associated with poor prognosis in patients with hypertension or coronary heart disease." (PMID 39234507, 2024). "Baseline imbalances between groups were entered into the model, including admission Hb, CRP and hypertension." (PMID 38594746, 2024). "We considered phenotypes that we have access to in both datasets, including WBC, HCT, HGB, PLT, CRP, serum creatinine, hypertension, stroke and T2D." (PMID 38310129, 2024). "Studies have shown that CRP levels are significantly elevated in hypertensive patients compared to those with normal blood pressure, indicating an inflammatory component in hypertension and its relevance to arterial stiffness and end-organ damage." (PMID 39246645, 2024). "Males were older (53 versus 57 years), with higher BP levels and a higher prevalence of hypertension, hyperlipidemia, cardiac disease, and OD; in addition, CRP levels were increased in males as compared to females subjects (P < 0.05 for all comparisons)." (PMID 39702460, 2024). "Statistically significant difference for CRP (P = 0.025) concentration between 3 time points was observed in the subgroup of subjects with arterial hypertension." (PMID 39435167, 2024). "Similar to males, females in the D/AO group were typically older, more likely to live in urban areas, have lower education levels, have higher levels of CRP, and have higher prevalences of hypertension, DM, and cardiovascular diseases." (PMID 39367987, 2024). "Positive correlations were observed between serum chemerin levels and markers such as alkaline phosphatase, C-reactive protein, eosinophils, and lymphocytes in the entire cohort, as well as in the subgroup excluding patients with hypertension and cirrhosis." (PMID 39335612, 2024). "For example, hypertensive animals and human patients have increased levels of IL-1β, IL-6, IL-17, TNF-α, CCL-2, C-reactive protein, and adhesion molecules, while immunosuppression attenuates hypertension." (PMID 39513878, 2024).
Hypertension (continued). "This analysis aimed to evaluate the potential effects of type 2 diabetes, hypertension, CRP, cigarettes per day and alcoholic drinks per week." (PMID 39444820, 2024). "The retention of uremic toxins, dysregulation of glucose metabolism, hypertension, dyslipidemia, hyperuricemia, and infection can lead to increased levels of proinflammatory cytokines, consequently increasing serum CRP levels." (PMID 38225279, 2024). "Patients with MGRS were significantly less likely to have hypertension, demonstrated a lower incidence of microscopic hematuria and lower serum c-reactive protein levels." (PMID 38200026, 2024). "Studies found that participants with rheumatoid arthritis who experience a higher burden of CVD due to hypertension benefited from supplementation with a natural anti-inflammatory compound that reduced CRP, IL6, and TNFα." (PMID 39558500, 2024). "The vitamin D and CRP relationship changed into a positive correlation, while the other remained unchanged for the hypertension group." (PMID 39200151, 2024). "A binomial logistic regression, adjusted for sex, age, BMI, HbA1c, LDL-C, hs-CRP, Troponin I, NT-proBNP, presence of hypertension, and lipid-lowering therapy confirmed that lower SDC4 is associated with history of MACE." (PMID 39164788, 2024). "Our study demonstrated, for the first time, that CRP is only partially able to affect biomarkers of endothelial dysfunction in SHR rats, which are genetically predisposed to the development of hypertension and metabolic syndrome." (PMID 38627621, 2024). "At the same time, hypertension will also lead to increased inflammation, and the interaction between CRP, IL-1, IL-6 and TNF-α and blood pressure will eventually lead to an increased risk of CA." (PMID 39464793, 2024). "Patients with higher levels of CRP were more likely to be female and have a history of stroke, lower LV mass, and have a lower prevalence of hypertension and were less likely to be prescribed angiotensin receptor blockers and statins." (PMID 38997620, 2024). "For Google Scholar, we used the query ‘allintitle: "Exercise" "Hypertension OR Hypertensive" "CRP OR inflammation OR inflammatory"’." (PMID 39246645, 2024). "In particular, the American diet results in increased CRP and IL-6 levels in the serum, while Dietary Approaches to Stop Hypertension and Mediterranean diets have decreased inflammatory factor levels." (PMID 39969369, 2024). "In the present study, the acute-phase systemic inflammatory process is characterized by a significant increase by hs-CRP serum levels in patients with hypertension, similar to diabetic patients." (PMID 39273236, 2024). "High blood pressure, high C-reactive protein and poor application of preventive practices were found to be the predictors of ICU admission." (PMID 38512971, 2024). "Lastly, in our MVMR analysis, adjustments for confounders such as fasting insulin, HOMA-IR, high blood pressure, circulating CRP levels, and smoking were meticulously made." (PMID 38390197, 2024). "Among the lost associations were nine metabolic and cardiovascular traits, such as levels of serum lipid and the inflammation biomarker C-reactive protein, cardiac valve and conduction disorders, and essential hypertension." (PMID 39332408, 2024). "Metabolic dysfunctions in BPD, such as elevated body mass index (BMI), high blood pressure, and inflammatory markers like C-reactive protein (CRP), exacerbate these risks." (PMID 39596351, 2024). "Fourteen studies focusing on exercise interventions and physical fitness related to CRP in individuals with high blood pressure were identified through an extensive search of PubMed, PubMed Central, ScienceDirect, Cochrane Library, and Google Scholar." (PMID 39246645, 2024). "In patients with essential hypertension, CRP and TNF-α correlated with 8-iso-prostaglandin-F2α, a marker of lipid peroxidation, characterized by vasoconstrictive and platelet-aggregation properties." (PMID 38398435, 2024).